SH3RF2 (SH3 domain containing ring finger 2)
Description:
Has E3 ubiquitin-protein ligase activity. Acts as an anti-apoptotic regulator of the JNK pathway by ubiquitinating and promoting the degradation of SH3RF1, a scaffold protein that is required for pro-apoptotic JNK activation. Facilitates TNF-mediated recruitment of adapter proteins TRADD and RIPK1 to TNFRSF1A and regulates PAK4 protein stability via inhibition of its ubiquitin-mediated proteasomal degradation. Inhibits PPP1CA phosphatase activity.
Synonyms: HEPP1; POSHER; PPP1R39; RNF158; FLJ23654
Tractability: PROTAC: UniProt records ubiquitination sites on it; ubiquitination databases record sites on it.
Gene: Protein-coding gene on chromosome 5 (145,936,425 to 146,085,976, forward strand). Ensembl gene ENSG00000156463.
Subcellular location: Nucleus
Subcellular location (Human Protein Atlas): Nucleoplasm
Gene Ontology:
Molecular function: phosphatase binding; protein binding; protein phosphatase 1 binding; ubiquitin protein ligase activity
Biological process: negative regulation of apoptotic process; negative regulation of protein ubiquitination; positive regulation of cell migration; positive regulation of JNK cascade; positive regulation of proteasomal ubiquitin-dependent protein catabolic process; protein autoubiquitination; negative regulation of JNK cascade; protein ubiquitination; regulation of JNK cascade
Cellular component: nucleoplasm; nucleus
Genetic constraint (gnomAD): Loss-of-function variants: 39 observed, 56.81 expected, observed/expected ratio (o/e) 0.69, 90% interval 0.53 to 0.9. The upper end of that interval is the gene's LOEUF score, 0.9, which puts it in group 3 of 6, group 1 being the genes least tolerant of losing a copy. Missense variants: 850 observed, 894.54 expected, observed/expected ratio (o/e) 0.95, 90% interval 0.9 to 1.01. Synonymous variants: 352 observed, 376.34 expected, observed/expected ratio (o/e) 0.94, 90% interval 0.86 to 1.02.
Homologues: Orthologues: chimpanzee SH3RF2 (99% identical), macaque SH3RF2 (96% identical), dog SH3RF2 (91% identical), rabbit SH3RF2 (87% identical), pig SH3RF2 (84% identical), guinea pig SH3RF2 (83% identical), rat Sh3rf2 (82% identical), mouse Sh3rf2 (82% identical), tropical clawed frog sh3rf2 (45% identical), Caenorhabditis elegans sorb-1 (12% identical), Caenorhabditis elegans B0303.7 (11% identical), Drosophila melanogaster Dlish (8% identical), and 2 more. Paralogues in human: SH3RF1 (33% identical), SH3RF3 (33% identical), SORBS1 (12% identical), SORBS2 (11% identical), SORBS3 (11% identical), SH3D19 (11% identical), SH3GL1 (7% identical), SH3GLB2 (7% identical), SH3GLB1 (6% identical), NCF4 (6% identical), SH3GL3 (5% identical), SH3GL2 (5% identical).
Diseases named in the same sentence as SH3RF2 in open-access papers:
SH3RF2 is named in the same sentence as 13 diseases in open-access papers, as found by Europe PMC text mining. Sharing a sentence is not in itself a finding about the gene and the disease. The quoted sentences say what the papers report.
autism (2 papers, 2022 to 2025). Persistent deficits in social interaction and communication and interaction as well as a markedly restricted repertoire of activity and interest as well as repetitive patterns of behavior. "In Sh3rf2-deficient mice, heightened GluR1-Ser831 phosphorylation and its aberrant postsynaptic membrane localization in the left striatum may impair the functional lateralization of striatal neurons and contribute to autism-like behaviors." (PMID 40890295, 2025). "Collectively, these results indicated that enhanced activity of DRD1-MSNs in the left striatum is responsible for autism-like behaviors in Sh3rf2 deletion mice." (PMID 40890295, 2025). "We conducted a series of behavioral experiments to substantiate that Sh3rf2 KO mice display autism-like symptoms, including social deficits and repetitive stereotyped behaviors, while maintaining normal motor capacity and memory." (PMID 40890295, 2025). "Subsequently, we investigated whether the heightened activity of DRD1-MSNs in the left striatum contributes to autism-like behaviors in Sh3rf2 KO mice." (PMID 40890295, 2025). "High levels of jumping behavior have been reported in Shank2 null, Sh3rf2 haploinsufficient, Camk2a-E183V, and Nlgn2 overexpression mice that model genetic risk factors for ASD and in the C58 inbred strain described as a mouse model of autism." (PMID 35227461, 2022).
colon cancer (2 papers, 2019 to 2022). "Although SH3RF2 has been shown to have high expression in colon cancer, with moderate membranous positivity, SH3RF2 is described as having low cancer specificity and is not prognostic." (PMID 36008952, 2022).
autism spectrum disorder (1 paper, 2025). A spectrum of developmental disorders that includes autism, and Asperger syndrome. "Notably, SH3RF2, whose single-copy knockout leads to autism spectrum disorder (ASD)-like behaviors in mice, is uniquely expressed in the striatum, forming a complex with CaMKII (an ASD-associated protein) and PPP1CC." (PMID 40890295, 2025).
Cognitive impairment (1 paper, 2022). Abnormal cognition is characterized by deficits in thinking, reasoning, or remembering. "Furthermore, nonoxid-HMGB1 ameliorated cognitive impairment in rats post-TBI via SH3RF2." (PMID 35479959, 2022).
pancreatic cancer (1 paper, 2021). "A novel 14-gene signature comprising CCDC148, SH3RF2, CACNA1D, POLD3, PARP1, AP1M2, C4orf19, ANO1, VGLL1, SCEL, INPP4B, NET1, INSIG2 and BVES and a corresponding risk score formula were established for pancreatic cancer risk stratification and prognosis prediction." (PMID 33731794, 2021).
cancer (8 papers, 2017 to 2025). A tumor composed of atypical neoplastic, often pleomorphic cells that invade other tissues. "SH3 domain containing ring finger 2 (SH3RF2) has been linked to the development of cancer." (PMID 38195842, 2024). "Of the genes that HHV-6A sequences were found to be integrated into or located near, most were significantly associated with cancers, and six, including CPLX1, IGFBP3, and the oncogene SH3RF2, were associated with malignant tumor formation (p = 8.45 × 10−7)." (PMID 30542640, 2018). "Among the module genes, BUB1, GATM, PLCE1, NEGR1, PTGER3 and SH3RF2 were differentially expressed in three or more cancer tissues." (PMID 28694494, 2017). "SH3RF2, in turn, is a recently described oncogene in humans, concordant with recent research showing the presence of CNVs being frequent across several cancer types." (PMID 39702044, 2024).
tumor (3 papers, 2013 to 2024). "Results showed that high expression of SH3RF2 was significantly associated with tumor sizes and DDP resistance." (PMID 38195842, 2024). "DDP-sensitive and DDP-resistant tumor tissues of OC patients were collected and used to perform immunohistochemistry (IHC) staining using anti-SH3RF2." (PMID 38195842, 2024). "Herein, we found higher expression levels of SH3RF2 in the tumor tissues from DDP-resistant OC patients and DDP-resistant OC cells." (PMID 38195842, 2024). "The findings uncovered a mechanistic basis by which SH3RF2 assisted tumor cells to reduce DNA damage, evade cell apoptosis, and promote cell proliferation induced by DDP in OC cell lines and xenograft tumor models." (PMID 38195842, 2024). "Here we find higher levels of SH3RF2 in the tumor tissues from cisplatin-resistant OC patients when compared to those from cisplatin-sensitive patients." (PMID 38195842, 2024). "Compared to those in the DDP+shNC group, the tumor tissues in the DDP+sh-SH3RF2 group showed a weaker staining for SH3RF2 and Ki67 but a stronger staining for cleaved caspase 3 and γH2AX." (PMID 38195842, 2024). "The analysis revealed most cells in tumor microenvironment including stromal cell expressed EGFR, NFE2, and FSL1 genes while a lower number of cells expressed CDH3, ARL4D, and SH3RF2." (PMID 38172584, 2024). "We found that shRNA-mediated depletion of SH3RF2 could exert antitumor effects in DDP-resistant OC cells and xenograft tumor models through promoting cell apoptosis and inhibiting cell proliferation." (PMID 38195842, 2024). "In addition, ARL4D, SH3RF2, and FOSL1 were found to be expressed in tumor immune cells (TICs)." (PMID 38172584, 2024). "There was a negative correlation between IHC scores of SH3RF2 and RBPMS staining in tumor tissues from OC patients." (PMID 38195842, 2024).
nervous system diseases (1 paper, 2021). "The mRNAs of Rgs9, Gpr88, Drd2, Sh3rf2, Tac1, Serpina 9, Rxrg, Drd1, Rasgrp2, Six3, Gpr6, Pdyn, Gng7, and Pde1b were all upregulated (p < 0.05); all of these have been reported to be more or less related to nervous system diseases." (PMID 33819195, 2021).
neurodevelopmental disorder (1 paper, 2025). A behavioral and cognitive disorder with onset during the developmental period that involves impaired or aberrant development of intellectual, motor, or social functions. "Insights gained by revealing SH3RF2-mediated molecular mechanisms underlying striatal asymmetry disruption and ASD-like behaviors would hold potential to reshape the perceptions of brain function and neurodevelopmental disorders." (PMID 40890295, 2025).
SH3RF2 also shares sentences with these, for which no sentence is quoted: breast carcinoma (1 paper); genetic disease (1); ovarian carcinoma (1); Prader-Willi syndrome (1).